ITGAX (integrin subunit alpha X)
Description:
Integrin alpha-X/beta-2 is a receptor for fibrinogen. It recognizes the sequence G-P-R in fibrinogen. It mediates cell-cell interaction during inflammatory responses. It is especially important in monocyte adhesion and chemotaxis. Functions as a receptor of the erythrocyte-specific adhesion molecule ICAM4 and mediates erythrophagocytosis.
Synonyms: CD11c; SLEB6
Tractability: Antibody: its Gene Ontology location is reachable by antibodies, with high confidence; UniProt predicts a signal peptide or a membrane-spanning region; the Human Protein Atlas places it where antibodies can reach. PROTAC: its protein half-life has been measured.
Gene: Protein-coding gene on chromosome 16 (31,355,134 to 31,382,999, forward strand). Ensembl gene ENSG00000140678.
Subcellular location: Cell membrane
Subcellular location (Human Protein Atlas): Plasma membrane; Vesicles
Pathways (Reactome):
Extracellular matrix organization: ECM proteoglycans; Integrin cell surface interactions
Immune System: Interleukin-4 and Interleukin-13 signaling; Neutrophil degranulation
Hemostasis: Cell surface interactions at the vascular wall
Gene Ontology:
Molecular function: cell adhesion receptor activity; protein binding; receptor tyrosine kinase binding; integrin binding; signaling receptor activity
Biological process: cell-cell adhesion mediated by integrin; heterotypic cell-cell adhesion; leukocyte cell-cell adhesion; phagocytosis; positive regulation of angiogenesis; positive regulation of cell migration; positive regulation of cell population proliferation; positive regulation of endothelial tube morphogenesis; positive regulation of gene expression; animal organ morphogenesis; cell adhesion; cell-cell adhesion; cell-matrix adhesion; integrin-mediated signaling pathway; positive regulation of myelination
Cellular component: cell surface; integrin alphaX-beta2 complex; membrane; plasma membrane; ficolin-1-rich granule membrane; integrin complex; secretory granule membrane; tertiary granule membrane; external side of plasma membrane
Genetic constraint (gnomAD): Loss-of-function variants: 96 observed, 135.24 expected, observed/expected ratio (o/e) 0.71, 90% interval 0.6 to 0.84. The upper end of that interval is the gene's LOEUF score, 0.84, which puts it in group 3 of 6, group 1 being the genes least tolerant of losing a copy. Missense variants: 1,407 observed, 1,484.2 expected, observed/expected ratio (o/e) 0.95, 90% interval 0.91 to 0.99. Synonymous variants: 619 observed, 604.72 expected, observed/expected ratio (o/e) 1.02, 90% interval 0.96 to 1.09.
Homologues: Orthologues: chimpanzee ITGAX (99% identical), macaque ITGAX (87% identical), rat Itgax (71% identical), mouse Itgax (71% identical), rabbit ITGAX (68% identical), tropical clawed frog itgad (41% identical), tropical clawed frog itgam (35% identical), zebrafish itgam.1 (34% identical), zebrafish itgam.2 (25% identical), Drosophila melanogaster if (20% identical), Caenorhabditis elegans pat-2 (19% identical), Drosophila melanogaster scb (17% identical), and 2 more. Paralogues in human: ITGAD (65% identical), ITGAM (60% identical), ITGAL (31% identical), ITGA11 (28% identical), ITGAE (28% identical), ITGA2 (27% identical), ITGA10 (27% identical), ITGA1 (26% identical), ITGA4 (22% identical), ITGA9 (21% identical), ITGA5 (20% identical), ITGAV (20% identical), and 5 more.
Diseases named in the same sentence as ITGAX in open-access papers:
ITGAX is named in the same sentence as 437 diseases in open-access papers, as found by Europe PMC text mining. Sharing a sentence is not in itself a finding about the gene and the disease. The quoted sentences say what the papers report.
Obesity (136 papers, 2011 to 2025). Accumulation of substantial excess body fat. "ITGAX encodes integrin alpha X chain protein (also named CD11c), previous studies reported that CD11c expression in adipose tissue was significantly increased in both diet‐induced obesity mice and humans." (PMID 32077223, 2020).
melanoma (77 papers, 2009 to 2026). A malignant, usually aggressive tumor composed of atypical, neoplastic melanocytes. "Based on our results, we hypothesize that the role played by ITGAX holds promise in predicting the response to immunotherapy in melanoma." (PMID 39015503, 2024). "The relationship between CD11c (ITGAX) expression and CD8+ T cell infiltration was further explored by analyzing publicly available datasets of melanoma patients." (PMID 37645859, 2024). "Additionally, ITGAL, ITGAX, and IIT possessed effective ICB biomarker potentials towards glioblastoma, melanoma, gastric cancer, and others, with analogous effectiveness compared to well-established ICB biomarkers." (PMID 37835514, 2023). "Therefore, we examined the correlation between IL-32 gene expression and the DC marker CD11c (also known as ITGAX) as well as the costimulatory molecules CD40, CD80, and CD86 in melanoma samples from The Cancer Genome Atlas (TCGA)." (PMID 32841222, 2020). "COL11A1 and ITGAX have both been previously related to tumor stage for other cancers (eg, melanoma, non-small cell lung cancer), but there are no reports for UNG and metastasis." (PMID 23717493, 2013).
lupus (71 papers, 2006 to 2026). "ITGAM and ITGAX are mainly involved in systemic lupus erythematosus, while TYEOBP and C3AR1 have been studied in the context of breast cancer." (PMID 31740624, 2019). "ABCs, initially discovered in systemic lupus erythematosus (SLE), are CD11c+ B cells with high expression levels of integrin subunit alpha X (ITGAX), T‐bet, and activation induced cytidine deaminase." (PMID 38469546, 2024). "Of note, we detected a subset of memory B cells expressing ITGAX (CD11c) and TBX21 (T-bet) that resemble ABCs previously reported to be expanded in ageing, following malaria vaccination and in systemic lupus erythematosus (SLE) patients." (PMID 35549406, 2022).
Autoimmunity (54 papers, 2011 to 2025). The occurrence of an immune reaction against the organism's own cells or tissues. "CD11c+T-bet+ B cells, also known as age-associated B cells (ABCs), have been reported in autoimmunity and aging, and likely correspond to this ITGAX+ memory B cell population." (PMID 35549406, 2022). "The activated memory B-cell state displays a hallmark of an effector B-cell response and shares several markers with previously defined aged/autoimmunity-associated B cells, e.g., high expression of ITGAX (CD11c)." (PMID 34835283, 2021).
autoimmune disease (52 papers, 2013 to 2026). A disorder resulting from loss of function or tissue destruction of an organ or multiple organs, arising from humoral or cellular immune responses of the individual to their own tissue constituents. "Furthermore, ITGAX is considered a risk gene in autoimmune diseases, and synovial CD79a-positive B cells may be a helpful biomarker of histologic disease activities in RA." (PMID 39315289, 2024). "SNVs in ITGAX (rs2230429) have been reported in some autoimmune diseases such as Bechet’s disease and systematic lupus erythematosus, but not in cancer." (PMID 36698400, 2022).
psoriasis (50 papers, 2005 to 2025). An autoimmune condition characterized by red, well-delineated plaques with silvery scales that are usually on the extensor surfaces and scalp. "We found one crossover locus of IL13 for psoriasis, two crossover loci BLK and ITGAM/ITGAX genes for SLE and four crossover loci near TFPI, CYP2A1, PECAM1, and CXCL12 for CAD data set." (PMID 32779262, 2020). "In addition, DC and T cell markers (CD3, ITGAX/CD11c and CD83) were expressed at higher levels in AD and psoriasis tissues." (PMID 36314037, 2022).
atherosclerosis (42 papers, 2011 to 2026). A disease characterized by the build-up of fatty material and calcium deposition in the arterial wall resulting in partial or complete occlusion of the arterial lumen. "It has been shown that ITGAX deficiency reduced the firm arrest of monocytes on vascular cells, monocyte/macrophage accumulation in intimae and consequently, reduced atherosclerosis development in apoE−/− mice fed a high-fat diet." (PMID 22110589, 2011). "In addition, various genes related to inflammation were also upregulated in the PCOS group, such as ITGAX, a pro-inflammatory macrophage gene encoding an integrin αX chain, which is linked to hypertriglyceridemia, hypercholesterolemia, and atherosclerosis." (PMID 40790236, 2025). "Beyond cancer, ITGAX plays a significant role in atherosclerosis and ischemic stroke through dendritic cell regulation and promotion of atherosclerotic tissue formation." (PMID 39845786, 2024). "Of these, after gene expression verification, only ITGB2, CTSS, LY86, and ITGAX were found to be highly expressed in both atherosclerosis and AAA." (PMID 39560590, 2024). "The overall association scores of CHI3L1 in coronary artery disease, peripheral arterial disease, carotid atherosclerosis, and atherosclerosis were 0.102, 0.091, 0.064, and 0.062, respectively, which are similar to the overall association scores of VCAM1 and ITGAX." (PMID 38177294, 2024). "ITGAX and CCR1 were identified as potential biomarkers for atherosclerosis, while macrophage-related genes, including ITGAX/CD11c and interferon regulatory factor 5, are strongly associated with symptomatic carotid artery disease." (PMID 39845786, 2024). "The text-mining scores of ITGAX, another well-known gene in CVD, atherosclerosis, Behcet’s syndrome, coronary artery disease, and atrial fibrillation, were 0.798, 0.236, 0.148, and 0.146, respectively." (PMID 38177294, 2024).
COVID-19 (40 papers, 2020 to 2024). A disease caused by infection with severe acute respiratory syndrome coronavirus 2. "The results showed that most of the genes, as in the discovery set (except CD38, LYN, and ITGAX), were significantly upregulated in patients with severe COVID-19 (p < 0.05)." (PMID 36052061, 2022). "Vice versa, genes down-regulated in CD14+-monocytes during severe COVID-19 were under significant positive influence by PIRAT, headed by the PU.1-suppressed genes IRF5 and ITGAX." (PMID 35998224, 2022). "This notion was further corroborated in qRT-PCR and FACS validations, which confirmed the control of S100A8, S100A9, ITGAX, and IRF5 by PIRAT and regulation of these factors during COVID-19." (PMID 35998224, 2022). "There were no signal inflows unique to either moderate or severe COVID-19 alone, whereas inflow through TNFRSF12A (due to TNFSF12) and ITGAX and ITGB2 (due to C3) drive outflows in only healthy controls." (PMID 39187683, 2024).
diabetes (20 papers, 2013 to 2025). "FcER1, ITGAX, SLC12A7 are a few of the top 30 significant genes, whose expression increased with the severity of diabetes." (PMID 34925339, 2021). "Moreover, GapmeR-mediated knockdown of human DNM3OS in human THP1 monocytes inhibited inflammatory genes (IL6, TNF, and ITGAX) and phagocytosis similar to actions of the mouse ortholog, suggesting DNM3OS upregulation in humans likely contributes to enhanced inflammation in diabetes." (PMID 34234740, 2021).
Granuloma (20 papers, 2010 to 2025). A compact, organized collection of mature mononuclear phagocytes, which may be but is not necessarily accompanied by accessory features such as necrosis. "Similar to other forms of sarcoidosis, the expression of RUNX1, MMP9, MMP12, CCR5, ITGAX, CD44, and human leukocyte antigens (HLA) is also seen in the granuloma of CS." (PMID 40521183, 2025).
glioma (18 papers, 2010 to 2025). A benign or malignant brain and spinal cord tumor that arises from glial cells (astrocytes, oligodendrocytes, ependymal cells). "Meanwhile, ligand-receptor interactions between THY1 (CD90) and ITGAX/ITGB2 (CD11C/CD18) were observed from glioma cells (Clusters C1, C2, and C4) to TAMs (Cluster C0)." (PMID 38515213, 2024).
leukemia (16 papers, 2015 to 2025). A malignant (clonal) hematologic disorder, involving hematopoietic stem cells and characterized by the presence of primitive or atypical myeloid or lymphoid cells in the bone marrow and the blood. "Finally, within CSF + LM group, differential protein profiles were observed between leukemia and lymphoma (such as FCGR1, CR2, ABL1, PTPRC, SELP, ITGB1, COL9A3 or ITGAX), which could subtype the CSF + LM depending on the primary tumor." (PMID 35053611, 2022).
hairy cell leukemia (15 papers, 2014 to 2025). Hairy cell leukemia (HCL) is a rare type of leukemia in which abnormal B-lymphocytes are present in the bone marrow, spleen and peripheral blood. "Moreover, CD11c is a diagnostic marker of hairy cell leukemia, and ITGAX expression is associated with aggressive prostate cancer." (PMID 31336593, 2019).
Alzheimer disease (14 papers, 2014 to 2025). A progressive, neurodegenerative disease characterized by loss of function and death of nerve cells in several areas of the brain leading to loss of cognitive function such as memory and language. "Additionally, ITGAX plays a role in inflammatory pathways in chronic kidney disease, ulcerative colitis, and neurodegenerative diseases like Alzheimer’s disease and cerebral amyloid angiopathy, where its overexpression in microglia contributes to neuroinflammation." (PMID 39845786, 2024). "CD11c (integrin alpha-X, ITGAX) and CD62 have previously been described in the context of Alzheimer’s disease." (PMID 38612385, 2024).
gastric cancer (13 papers, 2016 to 2024). A primary or metastatic malignant neoplasm involving the stomach. "The results indicated that high ITGAX expression was associated with a poor survival rate in patients with gastric cancer." (PMID 39845786, 2024). "Further investigation into the ITGAX-EMT axis could provide novel insights into the molecular mechanisms underlying gastric cancer and identify promising therapeutic targets." (PMID 39845786, 2024). "Our findings indicate that ITGAX facilitates gastric cancer cell invasion and proliferation by modulating the EMT signaling pathway." (PMID 39845786, 2024). "Further investigation into ITGAX mechanisms using clinical samples will deepen our understanding of its functional role in gastric cancer." (PMID 39845786, 2024). "In summary, our findings highlight ITGAX as a critical promoter of gastric cancer progression through EMT regulation, with potential links to autophagy and inflammatory responses." (PMID 39845786, 2024). "In conclusion, ITGAX holds significant potential as a biomarker for early diagnosis, prognosis, and treatment in gastric cancer, particularly for aggressive or metastatic cases." (PMID 39845786, 2024). "ITGAX represents a promising biomarker for early diagnosis, prognosis, and therapeutic targeting in gastric cancer patients." (PMID 39845786, 2024). "Our study demonstrates that ITGAX expression is significantly elevated in gastric cancer tissues compared to normal tissues and correlates with poor clinical prognosis." (PMID 39845786, 2024). "In this study, we demonstrated that ITGAX overexpression in gastric cancer cells significantly enhanced proliferation, migration and invasion while reducing apoptosis, highlighting its oncogenic potential." (PMID 39845786, 2024). "Our findings reveal that ITGAX promotes gastric cancer progression by driving epithelial-mesenchymal transition pathway (EMT), suggesting its potential as a biomarker for early diagnosis and prognosis in gastric cancer." (PMID 39845786, 2024). "Our study demonstrates that ITGAX expression is significantly elevated in tumor tissues compared to normal tissues and is positively correlated with clinical prognosis in gastric cancer patients from the GEO database." (PMID 39845786, 2024). "Despite its well-documented involvement in immune regulation, the specific mechanisms linking ITGAX to cancer progression, particularly in gastric cancer, remain poorly understood." (PMID 39845786, 2024). "Its involvement in gastric cancer was identified through an analysis of The Gene Expression Omnibus (GEO) database, which highlighted ITGAX as one of four key gastric cancer-related genes." (PMID 39845786, 2024). "ITGAX is significantly overexpressed in gastric cancer and strongly correlates with poor clinical prognosis, highlighting its potential clinical relevance." (PMID 39845786, 2024). "Conversely, ITGAX knockout inhibited these processes, further supporting its functional relevance in gastric cancer progression." (PMID 39845786, 2024). "Although ITGAX is well-studied in inflammatory conditions, such as neuroinflammation, non-alcoholic steatohepatitis, and dermatitis-like inflammation, its functional significance in gastric cancer remains poorly understood." (PMID 39845786, 2024). "Co-expression network analysis of datasets from the GEO database has identified four key genes involved in gastric cancer progression including ITGAX, chemokine (C-C motif) ligand 14 (CCL14), alcohol dehydrogenase iron-containing protein 1 (ADHFE1), and Homeobox B13 (HOXB13)." (PMID 39845786, 2024). "Additionally, ITGAX expression was significantly higher in patients with gastric cancer compared to the healthy group." (PMID 39845786, 2024). "We analyzed ITGAX expression levels in the human gastric mucosal epithelial cell line (GES-1) and various human gastric cancer cell lines (LMSU, ECC10, HS746.T, and SH-10-TC)." (PMID 39845786, 2024).
gastric cancer (continued). "Furthermore, our findings demonstrated that ITGAX regulates epithelial-mesenchymal transition (EMT) and immune modulation, which mediate tumor progression in gastric cancer." (PMID 39845786, 2024).
prostate carcinoma (13 papers, 2010 to 2025). A carcinoma that arises from epithelial cells of the prostate gland. "For example, ITGAX is recognized as a novel susceptibility gene for prostate cancer, where it contributes to tumor aggressiveness and angiogenesis." (PMID 39845786, 2024). "In addition, ITGAX is identified as a new type of aggressive prostate cancer susceptibility gene." (PMID 33976979, 2021). "Second, three of these five genes (CXCL14, ITGAX, and LPCAT2) harbored polymorphisms associated with aggressive disease development in a human GWAS cohort consisting of 1,172 prostate cancer patients." (PMID 25411967, 2014). "This approach, which is novel to the field of prostate cancer to the best of our knowledge, facilitated the identification of three novel aggressive prostate cancer susceptibility genes: CXCL14, ITGAX, and LPCAT2." (PMID 25411967, 2014). "In summary, we have identified CXCL14, ITGAX and, LPCAT2 as novel susceptibility genes for aggressive prostate cancer development." (PMID 25411967, 2014). "The expression level of ITGAX is positively correlated with aggressive prostate cancer." (PMID 33758613, 2021). "Expression of ITGAX is evident in aggressive prostate cancer." (PMID 31119098, 2019).
ovarian carcinoma (10 papers, 2012 to 2025). A malignant neoplasm originating from the surface ovarian epithelium. "ITGAX is closely associated with tumor development, and ITGAX promotes c-Myc-mediated VEGF-A transcription by activating the PI3K/Akt pathway and binding to VEGFR2 on the cell membrane, enhancing angiogenesis during ovarian cancer growth." (PMID 37033160, 2023).
hepatocellular carcinoma (7 papers, 2016 to 2024). A malignant tumor that arises from hepatocytes. "Moreover, integrin alpha x (ITGAX) stimulates cancer angiogenesis through PI3K/AKT signaling-mediated VEGFR2/VEGF-A overexpression in blood vessel endothelial cells in hepatocellular carcinoma (HCC)." (PMID 34220868, 2021).
nephritis (7 papers, 2017 to 2025). Inflammation of renal tissue. "Moreover, complement receptor genes CR1, ITGAM, ITGAX and ITGB2 showed a significant link between expression and kidney inflammation." (PMID 34326417, 2021).